LRP5 (LDL receptor related protein 5)
Diseases named in the same sentence as LRP5 in open-access papers (continued):
Sharing a sentence is not in itself a finding about the gene and the disease.
autosomal dominant polycystic kidney disease (2 papers, 2020 to 2024). Autosomal dominant form of polycystic kidney disease. "Wnt co-receptor LRP5 variants are reported to associate with autosomal dominant polycystic kidney disease; but their exact roles in this disease and renal fibrosis have not been explored." (PMID 32345960, 2020). "Moreover, LRP5 variants are reported to associate with autosomal dominant polycystic kidney disease, but the role of LRP5 in renal fibrosis and CKD has not been documented." (PMID 32345960, 2020).
autosomal dominant polycystic liver disease (2 papers, 2022 to 2023). An autosomal dominant inherited condition characterized by many cysts of various sizes scattered throughout the liver. "Autosomal Dominant Polycystic Liver Disease (ADPLD) leads to PLD only and is caused by a mutation in PRKCSH, SEC63, LRP5, ALG8 or SEC61B." (PMID 35216547, 2022). "LRP5 was first reported in relation to autosomal dominant polycystic liver disease with or without kidney cysts in 2014." (PMID 37372416, 2023). "However, overall, there is limited and unconvincing evidence to support a gene–disease relationship between LRP5 and autosomal dominant polycystic liver disease with or without kidney cysts." (PMID 37372416, 2023).
brain tumor (2 papers, 2021). "In the histological analysis, the progression of brain tumors was significantly suppressed in the A5 group and the overexpression of Lrp5 in the A5 + Lrp5 group further reduced the tumor-invaded area in the brain." (PMID 33802279, 2021). "Collectively, the co-injection of osteocytes into the brain suppressed the growth of brain tumors and the overexpression of Lrp5 in osteocytes enhanced the anti-tumor action." (PMID 33802279, 2021). "We examined the possibility of bone-to-brain mechanotransduction using a mouse model of a brain tumor by focusing on the response to Lrp5-mediated Wnt signaling and dopamine in tumor cells." (PMID 34031366, 2021). "In the histological analysis, the size of brain tumors in the (IL1ra + Lrp5) group was the smallest." (PMID 33802279, 2021). "Importantly, Lrp5- and/or IL1ra-overexpressing osteocytes or the local administration of β-catenin-overexpressing CM markedly inhibited brain tumors." (PMID 33802279, 2021).
colitis (2 papers, 2019 to 2022). Inflammation of the colon. "Selective deletion of LRP5/6 in CD11c+ APCs (which includes DC and macrophage populations in the intestinal mucosa) rendered mice more susceptible to dextran sodium sulfate (DSS)-induced colitis." (PMID 31781093, 2019). "The microbiome has been implicated as a driver of inflammation in mice with LRP5/6-deficient CD11c+ APCs with expression of a stabilized form of β-catenin specifically in CD11c+ APCs ameliorating disease pathology and pro-inflammatory responses in the DSS colitis model." (PMID 31781093, 2019).
diabetic nephropathy (2 papers, 2011 to 2020). "We assessed tag and potentially functional single nucleotide polymorphisms (SNPs; n = 31) in four key Wnt pathway genes (CTNNB1, AXIN2, LRP5 and LRP6) for association with diabetic nephropathy using a case-control design." (PMID 21876774, 2011). "Three additional SNPs (rs2075241 in LRP6; rs3736228 and rs491347 both in LRP5) were marginally associated with diabetic nephropathy, but none of the associations were replicated in an independent dataset." (PMID 21876774, 2011).
fibrosis (2 papers, 2020 to 2024). the formation of excess fibrous connective tissue in an organ or tissue in a reparative or reactive process. "SOST functions by binding to LRP5/6 and inhibiting canonical WNT/β-catenin signaling, a prominent targeted pathway of interest in cardiac fibrosis, regeneration, and angiogenesis." (PMID 39430425, 2024). "In the obstructed kidneys, Lrp5 knockout significantly ameliorated tubulointerstitial fibrosis and tubular injury without changing Wnt/β-catenin signaling." (PMID 32345960, 2020).
glioblastoma (2 papers, 2025). The most malignant astrocytic tumor (WHO grade IV). "Recently, bioinformatic analysis identified LRP5 as a prognostic marker in glioblastoma." (PMID 40940800, 2025).
Glucose intolerance (2 papers, 2015 to 2025). Glucose intolerance (GI) can be defined as dysglycemia that comprises both prediabetes and diabetes. "The knockout of the low-density lipoprotein receptor-related protein 5 (LRP5), which is a Wnt co-receptor, results in glucose intolerance in mice." (PMID 26729103, 2015).
head and neck cancer (2 papers, 2024 to 2025). A primary or metastatic malignant neoplasm affecting the head and neck. "In summary, our study presents the functional and clinical significance of a fusion transcript between the E3 ubiquitin ligase, UBE3C, and the Wnt signaling co-receptor, LRP5, found in a subset of patients with head and neck cancer." (PMID 38438481, 2024). "Taken together, these results suggest that overexpression of UBE3C-LRP5 fusion, but not LRP5, is sufficient to induce tumorigenesis in vitro and in vivo and promote migration and invasion of head and neck cancer cells in vitro." (PMID 38438481, 2024). "We found that overexpression of UBE3C-LRP5 fusion significantly increased the clonogenic, migratory, and invasive potential of head and neck cancer cells by activating the Wnt/β-catenin pathway, whereas transient knockdown of the fusion, but not full-length LRP5, suppresses these phenotypes." (PMID 38438481, 2024).
inflammatory bowel disease (2 papers, 2017 to 2021). A spectrum of small and large bowel inflammatory diseases of unknown etiology. "Relying on competing with Wnt ligands for LRP5/6 receptors, DKK1 has a role in promoting the development and differentiation of immunocytes, such as macrophages, DCs, and CD4+ T cells, which actively participates in the progression of inflammatory bowel disease." (PMID 34090510, 2021).
ischemia (2 papers, 2021 to 2024). A hypoperfusion of the BLOOD through an organ or tissue caused by a PATHOLOGIC CONSTRICTION or obstruction of its BLOOD VESSELS, or an absence of BLOOD CIRCULATION. "Then, adenoviruses expressing lacZ, LRP5, lamin, and shLRP5 were injected into the free walls of the left ventricle of rats, and then the rats were subjected to ischemia/reperfusion injury (I/R injury) three days after injection." (PMID 34205318, 2021). "In this study, we demonstrate a novel regulatory mechanism in ischemic myocardium consisting of the direct interaction between LRP5 and PHD2, which influences the stability of HIF-1α, a key molecule involved in the protection of cardiac death under ischemia." (PMID 34205318, 2021). "Therefore, the role of LRP5 in the myocardium under acute ischemia is independent of Wnt signaling, while Wnt signaling activation occurs during infarct healing in inflammation, fibrosis, and neovascularization." (PMID 34205318, 2021).
liver fibrosis (2 papers, 2025). "Furthermore, it has been previously documented that 1-PHE and LDL-receptor-related protein 5, as well as protein kinase cAMP-activated catalytic subunit alpha, have binding scores of ligands and target proteins of liver fibrosis." (PMID 40649803, 2025).
melanoma (2 papers, 2019 to 2020). A malignant, usually aggressive tumor composed of atypical, neoplastic melanocytes. "In humans, there is a positive feedback loop between IL-6 and WNT5A in melanoma cells, and WNT5A-FZD4/LRP5 signalling supports self-renewal of embryonic stem cells and eMSCs." (PMID 32552749, 2020).
myeloma (2 papers, 2009 to 2010). "Compared with the myeloma cells in the same BM microenvironment, SCs from patients with MM overexpressed LRP5/6 and Krm1/2, and thus had higher affinity to DKK-1, contributing to the different response to DKK-1." (PMID 20846389, 2010). "In the present study, we found the gene expression levels of LRP5/6 and Krm1/2 in SCs from patients with MM were much higher than those of primary myeloma cells, and those of normal SCs." (PMID 20846389, 2010). "The mRNA expression levels of DKK-1 binding receptor LRP5/6 and Krm1/2 in SCs from patients with MM were significantly higher than those in myeloma cells and in SCs from healthy donors." (PMID 20846389, 2010). "The mRNA expression levels of DKK-1 binding receptor LRP5/6 and Kremen1/2 (Krm1/2) were analyzed by Real-time PCR in human myeloma cell line (HMCL) RPMI-8226, NCI-H929, U266, LP-1, CZ-1, KM-3, Sko-007, primary myeloma cells and SCs from 12 MM patients and SCs from 10 healthy donors." (PMID 20846389, 2010). "All of these results mightily suggest that myeloma cells could promote expressions of LRP5/6 and Krm1/2 on SCs in coculture via DKK-1 secretion." (PMID 20846389, 2010). "Compared with myeloma cells, the SCs from MM patients overexpress DKK-1 binding receptors LRP5/6 and Krm1/2 in response to DKK-1 secreted by myeloma cells, which results in intracellular Wnt signaling inhibition." (PMID 20846389, 2010). "In comparison with myeloma cells, SCs from MM patients overexpress DKK-1 binding receptors LRP5/6 and Krm1/2, which probably lead to the blockade of intracellular Wnt signaling in SCs." (PMID 20846389, 2010). "Similar to the effects of coculture with rhDKK1, coculture of SCs from healthy donors with myeloma cells in the presence or absence of a Transwell insert did up-regulate SCs' mRNA levels of LRP5/6 and Krm1/2, and down-regulate their mRNA levels of β-catenin." (PMID 20846389, 2010). "LRP5/6 and Krm1/2 mRNA expression levels in SCs from patients with MM (C) were significantly higher than those in SCs from healthy donors (D) (p < 0.001) and those in CD138+ primary myeloma cells (B) (p < 0.01)." (PMID 20846389, 2010).
pancreatic cancer (2 papers, 2015 to 2021). "PG545 interacts with Wnt3a and Wnt7a to preventing them from binding to their receptors, LRP5/6 and Frizzled, resulting in significantly decreased β-catenin levels, suppressed tumor growth and metastasis in pancreatic tumors." (PMID 25669977, 2015).
periodontitis (2 papers, 2025). An acute or chronic inflammatory process that affects the tissues that surround and support the teeth. "In periodontitis, down-regulation of LRP5 results in the loss of alveolar bone and increases inflammation through the blockade of the PI3K/c-FOS signaling pathway, suggesting that LRP5 could be a promising target therapy for this disease." (PMID 40940800, 2025). "In addition, in the LR, LRP2, and LRP5 groups, lower levels of TNF-α and IL-1β were observed in both tissue and serum samples, similar to the finding that TNF-α and IL-1β levels were correlated with the degree of periodontitis and decreased after SRP." (PMID 39941567, 2025).
polycystic liver disease (2 papers, 2023 to 2024). "In addition, some studies in the literature have reported that, in up to 94% of patients, LRP5 variants may render ADPKD patients more susceptible to the development of polycystic liver disease." (PMID 37372416, 2023). "LRP5 is a co-receptor strongly expressed in both the liver and kidneys and involved in the Wnt signaling pathway, whose disruption may predominantly lead to polycystic liver disease." (PMID 37372416, 2023). "Of note, 4 patients in the COL4A3 cohort had liver cysts and despite no potentially pathogenic variants being found in genes associated with polycystic liver disease (PRKCSH, SEC63, and LRP5), we cannot completely rule out the presence of a second variant contributing to this phenotype." (PMID 39190485, 2024).
prostate tumor (2 papers, 2021 to 2022). "In response to Lrp5-overexpressing MSC CM, TRAMP prostate tumor cells also reduced EdU-based proliferation, transwell-based invasion, downregulated tumorigenic genes such as Lrp5, Runx2, MMP9 and Snail." (PMID 33859739, 2021).
Stickler syndrome (2 papers, 2021 to 2024). Stickler syndrome is an inherited vitreoretinopathy characterized by the association of ocular signs with more or less complete forms of Pierre-Robin sequence, bone disorders, and sensorineural deafness (10% of cases). "Exome sequencing identified 21 potential pathogenic variants of 13 genes in 20 of 75 (26.7%) probands, including genes for Stickler syndrome (COL11A1 and COL2A1; 6/20), FEVR (FZD4, LRP5, and TSPAN12; 5/20), and others (FBN1, GPR179, ZEB2, PAX6, GPR143, OPN1LW, FRMD7, and CACNA1F; 9/20)." (PMID 38243264, 2024).
tendinopathy (2 papers, 2011 to 2024). "Additionally, tendinopathy tissue showed differential expression of other WNT pathway genes, including increased expression of CTNNB (1.5-fold), WNT5a (2.7-fold), and FZD1 (1.7-fold) and decreased expression of LRP5 (0.59-fold) and FRZB (0.35-fold)." (PMID 21539748, 2011).
tongue cancer (2 papers, 2021 to 2024). A malignant neoplasm affecting the tongue. "In this study, we wanted to study the effects of LRP5 knockdown on the biological behavior of tongue cancer cell lines and their possible mechanisms." (PMID 38706907, 2024). "Our study found that after LRP5 knockdown in different tongue cancer cell lines, the growth of tumor cells was accelerated." (PMID 38706907, 2024).
acute kidney injury (1 paper, 2025). Sudden and sustained deterioration of the kidney function characterized by decreased glomerular filtration rate, increased serum creatinine or oliguria. "LRP5 is abundant in the renal tubules of humans and mice, where it plays a dual role, protecting against diseases such as acute kidney injury but exerting a detrimental effect in other conditions such as tubulointerstitial fibrosis and polycystic kidney diseases." (PMID 40940800, 2025).
adenoma (1 paper, 2021). A neoplasm arising from the epithelium. "In addition, we found variants in genes implicated in Wnt signalling, such as LRP5, WNT3A, and SFRP2, which shows a significantly increased level of methylation in adenomas." (PMID 34843512, 2021).
ameloblastoma (1 paper, 2023). The most common odontogenic tumor, arising from the epithelial component of the embryonic tooth and usually affecting the molar-ramus region of the mandible or maxilla. "The implications of LRP5 in the pathogenesis and treatment of ameloblastoma may be greater." (PMID 37628576, 2023). "It has been reported that activation of the Wnt/β-catenin pathway and IL-6/STAT3 signaling by LRP5 could promote neoplasm cells to acquire chemoresistance and the cancer stem cell phenotype, which should be considered when establishing chemotherapeutic approaches against ameloblastomas." (PMID 37628576, 2023). "We identified LRP5, SLC6A3, and SOX10 as potentially important genes related to the cell proliferation and invasion of ameloblastomas through a large-scale gene expression analysis using a microarray approach, validating the expression results through immunohistochemical assays." (PMID 37628576, 2023). "In ameloblastoma, the overexpression of SOX10, LRP5, and SLC6A3 may possibly be related to increased cell proliferation, local invasion, and high recurrence rates; as such therapeutic alternatives such as parthenolide and vorinostat may be employed as inhibitors of these genes." (PMID 37628576, 2023).
attention deficit-hyperactivity disorder (1 paper, 2024). A disorder characterized by a marked pattern of inattention and/or hyperactivity-impulsivity that is inconsistent with developmental level and clearly interferes with functioning in at least two settings (e.g. at home and at school). "Impairment in the Wnt pathway has been associated with various psychiatric disorders in humans, such as WNT1, WNT2, and WNT7A in autism spectrum disorder, WNT7B and LRP5 in SCZ, and LRP5 and LRP6 in attention-deficit/hyperactivity disorder." (PMID 39452096, 2024).
Barrett esophagus (1 paper, 2019). Esophageal lesion lined with columnar metaplastic epithelium which is flat or villiform. "We demonstrated for the first time a comprehensive analysis of all 10 frizzled receptors and their co-receptors LRP5 and LRP6 in an in vitro cell culture model of Barrett’s esophagus and in primary human specimens from normal squamous epithelium, Barrett’s mucosa, HGIN, and EAC." (PMID 30841855, 2019).
bone sarcoma (1 paper, 2015). A sarcoma that arises from the bone. "LRP6, LRP8 and Ror2 levels were significantly higher in bone sarcoma cells than in hMSC, while LRP5 levels were decreased in bone sarcoma cells." (PMID 25999350, 2015).
Chiari malformation (1 paper, 2017). A rare genetic brain malformation characterized by displacement of the brain stem and cerebellum through the foramen magnum. "We found a novel, private, predicted as damaging mutation in Nico in LRP5, a gene related to bone density alteration pathologies, and we suggest a link between this mutation and his Chiari malformation as previously shown in humans." (PMID 29123202, 2017). "Finally, it will be interesting to study a cohort of humans presenting the Chiari malformation to try to find the same or other different mutations in LRP5 gene, considering that the evidences connecting both are little." (PMID 29123202, 2017).
colorectal adenoma (1 paper, 2019). An adenoma that arises from the colon or rectum. "We identified genes with somatic mutations in the normal-colorectal adenoma samples, APC, CTNNB1, LRP5, FBXW7, and ATM, which overlapped with the TCGA data." (PMID 31336886, 2019).
colorectal tumor (1 paper, 2021). "In addition to LRP5/6, the role of the truncated form of the APC protein in colorectal tumor was also established by Schneikert and Behrens." (PMID 34769425, 2021).
deafness (1 paper, 2016). An inherited or acquired condition characterized by the complete loss of the ability to hear from one or both ears. "The LRP5 p.Asn198Ser mutation, seen in our most extreme HBM case with hip BMD Z‐scores >+10, has been reported in a family with HBM and deafness, sensorimotor neuropathy, and spinal stenosis, features that we did not observe." (PMID 26348019, 2016).
disc degeneration (1 paper, 2024). "Our analysis suggests that wnt5B, which is activated by LRP5, promotes apoptosis and inflammatory responses in nucleus pulposus cells by regulating the Wnt/Ca2+ signaling pathway, thereby promoting disc degeneration." (PMID 38654287, 2024). "In degenerated nucleus pulposus cells, LRP5 activate Wnt5B, which promotes nucleus pulposus cell apoptosis and inflammatory response by regulating the Wnt/Ca2+ signaling pathway, thereby promoting disc degeneration." (PMID 38654287, 2024). "In degenerative nucleus pulposus cells, LRP5 activates Wnt5B, which promotes apoptosis and inflammatory responses in nucleus pulposus cells by regulating the Wnt/Ca2+ signaling pathway, thereby promoting disc degeneration." (PMID 38654287, 2024).
dyslipidaemia (1 paper, 2015). "In this study, we analysed the role of LRP5 and the Wnt signalling pathway in mice fed a hypercholesterolaemic diet (HC) to trigger dyslipidaemia." (PMID 25656427, 2015).
esophageal cancer (1 paper, 2019). A primary or metastatic malignant neoplasm involving the esophagus. "The results showed a significant correlation between the expression levels of SPINK5 and β‐catenin (CTNNB1), LRP5, LRP6, DVL3, LEF1, AXIN2, MYC, and cyclin D1 (CCND1) in esophageal cancer." (PMID 30868765, 2019).
gestational diabetes mellitus (1 paper, 2023). "This study aims at evaluating the expression of placental LRP5 and sclerostin in pregnancies with gestational diabetes mellitus (GDM) and investigate possible associations with umbilical sclerostin concentrations and clinical outcomes in mothers and their neonates." (PMID 36947076, 2023).
hyperlipidemia (1 paper, 2020). "Previous studies have reported that statins may improve hyperlipidemia and enhances femoral head neovascularization through suppresses PPARγ expression and activates Wnt3a/LRP5/b-catenin/RUNX2 signaling pathway in steroid-induced animal models." (PMID 32509867, 2020).